CYB5A (cytochrome b5 type A)
Description:
Cytochrome b5 is a membrane-bound hemoprotein functioning as an electron carrier for several membrane-bound oxygenases.
Synonyms: MCB5; CYB5; METAG
Tractability: Small molecule: a structure with a bound ligand is known. Antibody: UniProt predicts a signal peptide or a membrane-spanning region. PROTAC: ubiquitination databases record sites on it; its protein half-life has been measured.
Target class: Transmembrane 1-electron transfer carriers; Transporter
Gene: Protein-coding gene on chromosome 18 (74,250,846 to 74,291,995, reverse strand). Ensembl gene ENSG00000166347.
Subcellular location: Endoplasmic reticulum membrane (Isoform 1); Microsome membrane; Cytoplasm (Isoform 2)
Subcellular location (Human Protein Atlas): Cytosol; Vesicles
Pathways (Reactome):
Metabolism: Vitamin C (ascorbate) metabolism
Protein localization: Insertion of tail-anchored proteins into the endoplasmic reticulum membrane
Gene Ontology:
Molecular function: enzyme binding; protein binding; heme binding
Cellular component: cytosol; membrane; endoplasmic reticulum membrane; mitochondrial outer membrane; cytoplasm; endoplasmic reticulum
Genetic constraint (gnomAD): Loss-of-function variants: 6 observed, 9.88 expected, observed/expected ratio (o/e) 0.61, 90% interval 0.33 to 1.2. That is too few expected variants to judge how well the gene tolerates losing a copy. Missense variants: 99 observed, 108.5 expected, observed/expected ratio (o/e) 0.91, 90% interval 0.77 to 1.08. Synonymous variants: 42 observed, 42.03 expected, observed/expected ratio (o/e) 1, 90% interval 0.78 to 1.29.
Gene-disease validity (ClinGen):
ClinGen rates the evidence that CYB5A causes each of these diseases.
methemoglobinemia type 4 (autosomal recessive): Definitive.
Homologues: Orthologues: chimpanzee CYB5A (100% identical), dog CYB5A (90% identical), rabbit CYB5A (90% identical), mouse Cyb5a (87% identical), guinea pig CYB5A (85% identical), pig CYB5A (83% identical), macaque CYB5A (76% identical), tropical clawed frog cyb5a (76% identical), rat Cyb5a (70% identical), zebrafish cyb5a (67% identical), rat Cyb5a (49% identical), Caenorhabditis elegans cytb-5.2 (40% identical), and 1 more. Paralogues in human: CYB5B (51% identical).
Diseases named in the same sentence as CYB5A in open-access papers:
CYB5A is named in the same sentence as 42 diseases in open-access papers, as found by Europe PMC text mining. Sharing a sentence is not in itself a finding about the gene and the disease. The quoted sentences say what the papers report.
breast carcinoma (4 papers, 2008 to 2024). "We found that CYB5A is closely related to tumor development as it is significantly downregulated in prostate cancer, adrenocortical cancer, breast cancer, and HCC and can inhibit the proliferation and metastasis of pancreatic cancer cells." (PMID 35851063, 2022).
pancreatic cancer (4 papers, 2017 to 2022). "In humans, mutations in CYB5A WT cause type IV methemoglobinemia; low CYB5A mRNA and protein expression is associated with shorter survival in pancreatic cancer." (PMID 35436854, 2022). "Unfortunately, the antitumor effect of CYB5A in pancreatic cancer has only been briefly discussed so far." (PMID 35851063, 2022). "Further, Cyb5a has been shown to play a role in promoting autophagy in pancreatic cancer cells." (PMID 27136898, 2017).
methemoglobinemia (3 papers, 2008 to 2021). An inherited or acquired condition characterized by abnormally increased levels of methemoglobin in the blood. "A deficiency of cyb5a can lead to the physiological condition of methemoglobinemia." (PMID 34290620, 2021).
glioma (2 papers, 2020 to 2022). A benign or malignant brain and spinal cord tumor that arises from glial cells (astrocytes, oligodendrocytes, ependymal cells). "Here, AK2, CYB5A and GOLT1B were significantly higher in all glioma sample groups, relative to controls." (PMID 32635403, 2020).
hepatocellular carcinoma (2 papers, 2022 to 2026). A malignant tumor that arises from hepatocytes. "Similarly, IHC was performed on HCC samples from 80 clinical patients, resulting in a malignant degree of hepatocellular carcinoma, lower CYB5A and LC3 expression levels, and higher STOML2 and p-STAT3 expression levels." (PMID 35851063, 2022).
Obesity (2 papers, 2019 to 2024). Accumulation of substantial excess body fat. "Modification in CYB5A is associated with weight-regulating pathways in obesity and NIDDM, but this gene may diagnose insulin resistance." (PMID 30678306, 2019).
prostate carcinoma (2 papers, 2008 to 2022). A carcinoma that arises from epithelial cells of the prostate gland. "In various cancer types, such as prostate cancer and adrenal cortical cancer, scholars found that CYB5A is significantly downregulated in cancer compared with the corresponding adjacent normal tissues through statistical analysis without subjective impression." (PMID 35851063, 2022).
bone metabolism disorders (1 paper, 2025). "Thus, CYB5A is a potential target for modulating osteogenic differentiation and treating bone metabolism disorders." (PMID 40246926, 2025).
heart failure (1 paper, 2025). Inability of the heart to pump blood at an adequate rate to meet tissue metabolic requirements. "There is no direct evidence linking the Cyb5a gene to heart failure although it does act as an electron carrier for Cyb5r3 a known contributor to heart failure and so presumably it is linked to heart failure through a similar pathway." (PMID 41446135, 2025).
leukemia (1 paper, 2009). A malignant (clonal) hematologic disorder, involving hematopoietic stem cells and characterized by the presence of primitive or atypical myeloid or lymphoid cells in the bone marrow and the blood. "In the original study, two of these genes were found as differentiating among two leukemia subtypes (BASP1 and CYB5A) and the other three were never mentioned." (PMID 19146700, 2009).
liver fibrosis (1 paper, 2013). "Out of 76 differentially expressed proteins, six proteins ATPD, FIBB, ATPB, HBB, CYB5A, and QCR1 were quantified across the specimens and delineated into liver fibrosis and carcinoma specific proteins." (PMID 23724895, 2013).
metastatic tumors (1 paper, 2022). "This suggests that, possibly, metastatic tumors in patients with high CYB5A expression exhibit more sensitivity to JAK1 inhibitors." (PMID 35851063, 2022). "To demonstrate the effect of CYB5A on JAK1 inhibitor function, we applied Ruxolitinib in metastatic tumors with high CYB5A expression and found that it slowed disease progression and prolonged survival in mice." (PMID 35851063, 2022). "Moreover, JAK inhibitor Ruxolitinib’s application in metastatic tumors with high CYB5A expression inhibited disease progression and prolonged survival in mice." (PMID 35851063, 2022).
osteoporosis (1 paper, 2025). A condition of reduced bone mass, with decreased cortical thickness and a decrease in the number and size of the trabeculae of cancellous bone (but normal chemical composition), resulting in increased fracture incidence. "Further research should examine how CYB5A functions under different physiological and pathological conditions, such as osteoporosis and bone fracture healing, to assess its therapeutic potential." (PMID 40246926, 2025).
sarcoma (1 paper, 2019). A usually aggressive malignant neoplasm of the soft tissue or bone. "Its human syntenic region, Hs-18q23, is recurrently deleted in sarcomas and contains two genes, GALR1 and CYB5A, that are annotated as tumor suppressors." (PMID 30947707, 2019).
tumor (13 papers, 1971 to 2025). "To further study the possible mechanisms underlying the superior tumor-suppressor effect of CYB5A, we utilized co-immunoprecipitation (co-IP) and mass spectrometry analysis." (PMID 35851063, 2022). "Our finding showed that up‐regulation of LRRC1 and down‐regulation of CYB5A were associated with tumor grade." (PMID 29123978, 2017). "One example was CYB5A which expressed isoform ENST00000340533 in 60% of tumor cells but 91% of normal cells." (PMID 37433798, 2023). "We evaluated CYB5A’s role in tumor metastasis by injecting HCC cells into nude mice via their tail veins and monitoring lung metastatic nodules." (PMID 35851063, 2022). "These suggested that CYB5A further inhibited tumor progression in hypoxia." (PMID 35851063, 2022). "This yielded 88 genes associated with tumor grade, in which seven DEGs (C8orf33, TSNAXIP1, TM4SF1, CTH, ANXA2, KIAA1522 and LRRC1) can distinguish HCC of G3 from G1, two DEGs (CYB5A and RRAGD) can distinguish HCC of G3 from G2, and two DEGs (CFHR4 and F13B) can distinguish HCC of G3 from G4." (PMID 29123978, 2017). "This seems to suggest that CYB5A may be a tumor-suppressor gene in pan-cancer." (PMID 35851063, 2022).
cancer (9 papers, 2013 to 2024). A tumor composed of atypical neoplastic, often pleomorphic cells that invade other tissues. "CYB5A (cytochrome B5 type A (microsomal)) was related to autophagy induction, concomitant with reduced proliferation and migration/invasion in cancer cells." (PMID 27091189, 2016). "The significant downregulation of CYB5A has been reported in cancers; however, the mechanism underlying the antitumor effect of CYB5A has not been explored much." (PMID 37245006, 2023).
CYB5A also shares sentences with these, for which no sentence is quoted: infection (5 papers); retinal degeneration (2); 21-hydroxylase deficiency (1); acute lung injury (1); adrenocortical adenoma (1); adrenocortical cancer (1); breast tumors (1); campomelic dysplasia (1); colorectal cancer (1); cryptorchidism (1); Cushing syndrome (1); diabetes (1); fibrosis (1); glioblastoma (1); hypospadias (1); Immunodeficiency (1); inflammation (1); Insulin resistance (1); lipoid congenital adrenal hyperplasia (1); liver cancer (1); malaria (1); nematode infections (1); primary adrenal insufficiency (1); Star (1); stomach cancer (1); viral infection (1).